HADHA (hydroxyacyl-CoA dehydrogenase trifunctional multienzyme complex subunit alpha)
Diseases named in the same sentence as HADHA in open-access papers (continued):
Sharing a sentence is not in itself a finding about the gene and the disease.
male infertility (1 paper, 2015). The inability of the male to effect fertilization of an ovum after a specified period of unprotected intercourse. "From these results, one could infer that HADHA in large litter size sperm downregulates VDAC2 to affect male infertility." (PMID 26348888, 2015).
melanoma (1 paper, 2023). A malignant, usually aggressive tumor composed of atypical, neoplastic melanocytes. "Consistent with reduced FAO capacity, β-oxidation pathway enzyme HADHA exhibited a decreased expression trend in melanoma mDC." (PMID 37938561, 2023).
metabolic myopathy (1 paper, 2021). A group of rare inherited disorders characterized by a deficiency of enzymes that are involved in metabolic pathways that affect muscles. "Thus, we report a new subtype of CMT with metabolic myopathy due to MTPD deficiency caused by mutations of HADHB gene, suggesting that all CMT patients without definite pathogenic mutations should be screened for mutation in HADHA and HADHB genes." (PMID 34712195, 2021). "The HADHA and HADHB gene should be added into the screening panel for CMT and metabolic myopathy." (PMID 34712195, 2021).
Nephroblastoma (1 paper, 2025). An embryonal neoplasm characterized by the presence of epithelial, mesenchymal, and blastema components. "They found that hydroxyacyl-CoA dehydrogenase trifunctional multienzyme complex subunit alpha (a lipid metabolism enzyme, HADHA) is expressed at a lower level in nephroblastoma tissues." (PMID 41480378, 2025).
periodontitis (1 paper, 2025). An acute or chronic inflammatory process that affects the tissues that surround and support the teeth. "Furthermore, the downregulation of DBT, ACOX1, ACAA2, and HADHA in the liver provides valuable insights for developing therapeutic strategies for periodontitis-associated NAFLD." (PMID 40951429, 2025). "Based on these findings, DBT, ACOX1, ACAA2 and HADHA emerge as potential key targets linking periodontitis to NAFLD." (PMID 40951429, 2025).
Sensory neuropathy (1 paper, 2021). Peripheral neuropathy affecting the sensory nerves. "The present study supports the notion that HADHA- or HADHB-related motor and sensory neuropathy should be considered as a CMT subtype." (PMID 34712195, 2021).
tumor (22 papers, 2015 to 2025). "Data showing low expression of HADHA, a key enzyme involved in oleate metabolism in selected immune populations, while being present in tumor cells and tumor-associated macrophages, further supported the central role of intratumoral oleate." (PMID 40902455, 2025). "The results indicated that ACSL3, ADH1B, ALDH2, and HADHA had strongly associated with the tumor grade." (PMID 37540213, 2023). "Intracranial injection of shHADHA or shControl LN229 cells into mice established an orthotopic tumor model to explore the impact of HADHA on tumor growth in vivo." (PMID 40750765, 2025). "The regulatory effect of HADHA on H3K27ac highlights how metabolic alterations can influence epigenetic marks, potentially affecting gene expression and the functionality of tumor cells." (PMID 40750765, 2025). "In GBM, changes in histone acetylation, driven by enzymes like HADHA, can facilitate the activation of signaling pathways that are critical for tumor progression." (PMID 40750765, 2025). "To further explore the molecular mechanism by which HADHA facilitates tumor malignancy, we carried out RNA sequencing of HADHA-shRNA-transfected and control Eca-109 cells." (PMID 39327932, 2024). "In a group of 80 paired samples from patients with EC, HADHA expression was significantly higher in tumor tissues than in peritumoral tissues (P < 0.001)." (PMID 39327932, 2024). "High HADHA expression was significantly related to tumor infiltration, lymphatic metastasis, tumor stage, and distant metastasis, indicating more aggressive tumor behavior." (PMID 39327932, 2024). "Most importantly, the inhibition of CDK1 via knockdown partially counteracted the tumor growth enhancement induced by HADHA elevation." (PMID 37986001, 2023). "Elevated levels of HADHA were correlated with various clinical parameters including pathological grade, tumor size, tumor infiltrate, lymphatic metastasis, distant metastasis, clinical stage and recurrence of state." (PMID 37986001, 2023). "Steady-state levels of CPT1, the electron transfer flavoprotein subunit α (ETFA) and HADHA, three proteins involved in the mitochondrial transport and oxidation of FA, increased significantly in tumor biopsies." (PMID 35534478, 2022). "Here, the roles of HADHA on in-vivo tumor growth and metastasis were surveyed using micro-spiral CT scanning in the orthotopic HCCLM3 xenograft models." (PMID 32033570, 2020). "As HADHA catalyzes critical steps in fatty acid β-oxidation (converting fatty acids to acetyl-CoA for energy production), its loss shifts HCC metabolism toward lipogenesis, fueling tumor proliferation and metastasis." (PMID 40426910, 2025). "ALDH1A1 is involved in cellular detoxification and retinoic acid signaling, which may contribute to immune modulation, while HADHA's role in fatty acid β-oxidation influences tumor microenvironment reprogramming." (PMID 40861812, 2025). "Among these, HADHA—a mitochondrial enzyme linked to fatty acid β-oxidation and implicated in multiple cancers —showed reduced expression in poorly differentiated HCC, suggesting its tumor-suppressive role." (PMID 40426910, 2025). "Moreover, the expression level of HADHA has been shown to intricately correlate with tumor advancement and prognosis in humans, with varying effects." (PMID 38637116, 2024). "In summary, we showed that HADHA expression was upregulated in EC tissues and was positively correlated with more aggressive clinical manifestations, including tumor infiltration, lymphatic metastasis, tumor stage and distant metastasis." (PMID 39327932, 2024). "Furthermore, when we knocked down CDK1, we observed a partial restriction in the tumor growth that had been enhanced by elevating HADHA expression." (PMID 37986001, 2023). "Moreover, HADHA upregulation correlated with several pathological parameters, including pathological stage, tumor size, tumor infiltrate, metastasis, and recurrence." (PMID 37986001, 2023).
tumor (continued). "Significantly, ACSL3 and HADHA were upregulated in advanced tumor grade." (PMID 37540213, 2023). "miR-612 can suppress the formation of invadopodia, EMT, and HCC metastasis and by HADHA-mediated lipid programming, which may provide a new insight of miR-612 on tumor metastasis and progression." (PMID 32033570, 2020). "Regarding the over-expression of HADHA protein, a significant positive correlation between HADHA expression and LC tumor was observed both in cisplatin-resistant LC cells and bioptic specimens from chemotherapy-resistant patients affected by NSCLC, or SCLC or AC has been reported." (PMID 26104294, 2015). "Additionally, we conducted Mann-Whitney U analysis, which demonstrated a statistically significant positive correlation between HADHA levels and various clinicopathological parameters, including pathological stage, tumor size, tumor infiltrate, metastasis and recurrence of state." (PMID 37986001, 2023). "Therefore, we supposed that miR-612 might regulate tumor invasiveness and metastasis by HADHA-mediated lipid reprogramming and probably resulting in the abnormity of invadopodia in structure and function in HCC." (PMID 32033570, 2020). "The findings not only confirm the association between the overexpression of HADHA in GBM and poor prognosis but also elucidate the impact of HADHA-mediated metabolic changes on GBM progression, particularly in regulating tumor growth and signal transduction." (PMID 40750765, 2025). "we show that the overexpression of HADHA in GBM correlates with a poor prognosis in patients and plays a role in promoting tumor growth and invasion." (PMID 40750765, 2025). "For example, we identified five lysine acetylation sites in HADHA, four lysine acetylation sites in HADHB, and three lysine acetylation sites in both ACADVL and PCCA, all of which showed lower acetylation levels in tumor tissues." (PMID 33093847, 2020). "Since the expression of HADHA in EC has never been evaluated, we first performed IHC staining of EC tissue samples from different tumor stages." (PMID 39327932, 2024). "Furthermore, subsequent studies revealed that HADHA significantly influences the proliferation, invasion, and migration of GBM cells, as well as tumor growth in vivo." (PMID 38566075, 2024). "HADHA is a mitochondrial trifunctional enzyme specifically involved in the last three of the four reactions of long‐chain fatty acids beta‐oxidation pathway, and the acetylation levels of the K60, K129, and K569 of HDAHA were also downregulated in tumor tissues, which is consistent with our results." (PMID 33783990, 2021).
cancer (12 papers, 2012 to 2025). A tumor composed of atypical neoplastic, often pleomorphic cells that invade other tissues. "Thirdly, although consistent, the observed differential expression of HADHA with cancer progression (as reflected by risk of metastasis and recurrence) is statistically inconclusive." (PMID 22240105, 2012). "The role of metabolic enzymes as therapeutic targets in cancer has been previously reported, reinforcing the potential of HADHA as a target." (PMID 40750765, 2025). "Although this study offers valuable insights into the role of HADHA in GBM, additional research is needed to validate these findings and investigate the role of HADHA in other cancer types." (PMID 40750765, 2025). "The role of HADHA in cancer has seldom been investigated, and previous studies have reported controversial functions of HADHA in several types of cancer." (PMID 39327932, 2024). "The hydroxyacyl-CoA dehydrogenase alpha subunit (HADHA) plays an essential role in long-chain fatty acid metabolism, and dysregulation of HADHA has been demonstrated to be involved in a series of metabolic diseases and cancers." (PMID 39327932, 2024). "Compared to controls, more cancer cells of D-BAT-treated mice had low expression of hydroxyacyl-CoA dehydrogenase (HADHA), the enzyme catalyzing the last three steps of mitochondrial fatty acid (FA) beta-oxidation." (PMID 35835372, 2022). "Our findings highlight the importance of targeting metabolic enzymes in cancer therapy and suggest that HADHA could represent a potential new therapeutic target for GBM." (PMID 40750765, 2025). "However, recent research has revealed that HADHA, as a key lipid metabolic enzyme, also plays a novel role in the development of various cancers, including lung cancer, renal cell carcinoma, hepatocellular carcinoma, malignant lymphoma and breast cancer." (PMID 37986001, 2023). "The 3D invasion capability of HADHA-knockdown LN229 and U251 cells was significantly reduced in the Cancer Cell Spheroid Invasion Assay." (PMID 40750765, 2025). "Compared to WT mice, cancer cells of KO mice had no detectable expression of hydroxyacyl-CoA dehydrogenase (HADHA), the enzyme catalyzing the last 3 steps of mitochondrial fatty acid β-oxidation." (PMID 34314388, 2021). "We found that the HADHA expression had fallen to 73% (95% CI 64%-83%) in subjects with cancer; with a higher expression in ER + subjects (76% of the no cancer group, 95% CI 61%-91%) than in ER-subjects (70% of the no cancer group, 95% CI 55%-85%)." (PMID 22240105, 2012). "Indeed, the q value for the HADHA gene was 0.15 for the cancer versus no cancer comparison, 0.13 for the ER-versus no cancer comparison but 0.88 for the ER + versus no cancer comparison." (PMID 22240105, 2012).
metabolic disease (12 papers, 2017 to 2025). A congenital disorder (due to inherited enzyme abnormality) or acquired (due to failure of a metabolically important organ) disorder resulting from an abnormal metabolic process. "However, variants in the HADHA gene were the likely cause of the metabolic disorder in these cases." (PMID 35433169, 2022). "In HFD-fed mice, HADHA overexpression improved metabolic disorders, and these effects are abrogated by knockdown of BHB-producing enzyme." (PMID 35046401, 2022). "Mutations in MTP genes (HADHA and HADHB), both located on chromosome 2p23, cause MTP deficiency, a rare autosomal recessive metabolic disorder characterized by decreased activity of MTP." (PMID 29095929, 2017). "HADHA acts as a mitochondrial peroxidase that promotes fatty acid metabolism by catalyzing the last three steps of the mitochondrial β‐oxidation of long‐chain fatty acids; decreased HADHA expression results in impaired fatty acid oxidation, leading to a variety of metabolic diseases." (PMID 39139977, 2024). "HADHA overexpression improved metabolic parameter, and this effect was blocked by hepatic BDH1 knockdown, suggesting a role of BHB in regulating metabolic disorders." (PMID 35046401, 2022).
infection (5 papers, 2013 to 2024). The state of being infected such as from the introduction of a foreign agent such as serum, vaccine, antigenic substance or organism. "Moreover, HADHA can be used as an effective candidate drug for the development of new vaccines because it can induce partial immune protection against pathogen infection." (PMID 36140692, 2022). "In addition, western blotting analysis could further confirm that HADHA was indeed down-regulated by SARS-CoV-2 structural protein infection." (PMID 37236979, 2023). "(F) Immunoblotting of host glycolytic (PGK), TCA cycle (PDHA1), and fatty acid oxidation (HADHA, ACOX-1) proteins under Sirt1 and Sirt3 knockdown condition of S. Typhimurium-infected RAW 264.7 macrophages at 16 hr post-infection." (PMID 39693143, 2024).
cardiovascular diseases (3 papers, 2022 to 2024). "In contrast to the majority of studies that mainly reported SNPs with an alternative allele increasing the risk of a severe COVID-19 infection outcome, in the case of the cardiovascular disease gene panel, we identified a potentially protective variant located in the HADHA gene with an OR of 0.59." (PMID 35955824, 2022).
retinopathy (3 papers, 2022 to 2023). "Patients with at least one c.1528G > C allele in the HADHA gene, commonly develop severe retinopathy." (PMID 36599942, 2023).
mitochondrial disease (2 papers, 2019 to 2022). "To better assess the sarcomere and mitochondrial disease phenotype we performed transmission electron microscopy (TEM) on WT and HADHA Mut CMs after 12D of Glc + FA exposure." (PMID 31604922, 2019).
autosomal recessive disease (1 paper, 2017). Autosomal recessive form of disease. "Homozygous mutations in DDOST, HADHA or GPR56 genes cause autosomal recessive diseases, thus, the heterozygous variants in these genes carried by the proband like their healthy parents were excluded for the pathogenic mutation." (PMID 29137252, 2017).
endocrinopathies (1 paper, 2014). "One of these variants, the N309K mutation in the PCSK1 gene, appeared to be the probable cause of the CDD and endocrinopathies, given that other mutations in PCSK1 are known to cause similar symptoms, whereas the other three variants (HADHA, FBXL17 and GTF3C2) are not known to be involved in CDD." (PMID 25272002, 2014).
HADHA also shares sentences with these, for which no sentence is quoted: peripheral neuropathy (7 papers); preeclampsia (6); Hypoglycemia (4); myopathy (3); pigmentary retinopathies (3); cardiac disease (2); Deficiencies (2); glutaric aciduria type II (2); infertile (2); pancreatic cancer (2); (MCAD) deficiency (1); 3-hydroxyacyl-CoA dehydrogenase deficiency (1); acute respiratory failure (1); age (1); ampullary adenocarcinoma (1); antiphospholipid syndrome (1); arginase deficiency (1); asthma (1); astrocytomas (1); ataxia telangiectasia (1); atherosclerosis (1); Atrophy (1); Barth syndrome (1); cardiac arrhythmia (1); cardiac hypertrophy (1); carnitine deficiency (1); Charcot-Marie-Tooth disease (1); citrullinemia (1); congenital adrenal hyperplasia (1); developmental delay (1).
A further 42 diseases each share a sentence with HADHA in 1 paper.